ARPC3 (actin related protein 2/3 complex subunit 3)
Description:
Component of the Arp2/3 complex, a multiprotein complex that mediates actin polymerization upon stimulation by nucleation-promoting factor (NPF). The Arp2/3 complex mediates the formation of branched actin networks in the cytoplasm, providing the force for cell motility. In addition to its role in the cytoplasmic cytoskeleton, the Arp2/3 complex also promotes actin polymerization in the nucleus, thereby regulating gene transcription and repair of damaged DNA. The Arp2/3 complex promotes homologous recombination (HR) repair in response to DNA damage by promoting nuclear actin polymerization, leading to drive motility of double-strand breaks (DSBs).
Synonyms: p21-ARC; ARC21
Tractability: Small molecule: a structure with a bound ligand is known. PROTAC: UniProt records ubiquitination sites on it; ubiquitination databases record sites on it; its protein half-life has been measured.
Gene: Protein-coding gene on chromosome 12 (110,434,582 to 110,450,422, reverse strand). Ensembl gene ENSG00000111229.
Subcellular location: Cytoplasm, cytoskeleton; Cell projection; Nucleus
Subcellular location (Human Protein Atlas): Nucleoplasm
Pathways (Reactome):
Developmental Biology: EPHB-mediated forward signaling
Disease: FCGR3A-mediated phagocytosis
Immune System: Regulation of actin dynamics for phagocytic cup formation
Signal Transduction: RHO GTPases Activate WASPs and WAVEs
Vesicle-mediated transport: Clathrin-mediated endocytosis
Gene Ontology:
Molecular function: actin filament binding; protein binding; structural constituent of cytoskeleton
Biological process: Arp2/3 complex-mediated actin nucleation; actin polymerization-dependent cell motility; cellular response to nerve growth factor stimulus; regulation of synaptic vesicle endocytosis
Cellular component: Arp2/3 protein complex; extracellular exosome; focal adhesion; lamellipodium; membrane; nucleus; actin cytoskeleton; cytosol; site of double-strand break; cell leading edge; cytoskeleton; filamentous actin; growth cone leading edge
Genetic constraint (gnomAD): Loss-of-function variants: 5 observed, 15.51 expected, observed/expected ratio (o/e) 0.32, 90% interval 0.17 to 0.68. The upper end of that interval is the gene's LOEUF score, 0.68, which puts it in group 2 of 6, group 1 being the genes least tolerant of losing a copy. Missense variants: 103 observed, 145.33 expected, observed/expected ratio (o/e) 0.71, 90% interval 0.6 to 0.83. Synonymous variants: 42 observed, 48.48 expected, observed/expected ratio (o/e) 0.87, 90% interval 0.68 to 1.12.
Homologues: Orthologues: chimpanzee ARPC3 (100% identical), guinea pig ARPC3 (100% identical), pig ARPC3 (100% identical), rabbit ARPC3 (100% identical), dog ARPC3 (99% identical), mouse Arpc3 (98% identical), tropical clawed frog arpc3 (92% identical), zebrafish arpc3 (87% identical), rat Arpc3 (75% identical), Drosophila melanogaster Arpc3B (61% identical), Drosophila melanogaster Arpc3A (60% identical), Caenorhabditis elegans arx-5 (57% identical).
Diseases named in the same sentence as ARPC3 in open-access papers:
ARPC3 is named in the same sentence as 22 diseases in open-access papers, as found by Europe PMC text mining. Sharing a sentence is not in itself a finding about the gene and the disease. The quoted sentences say what the papers report.
mastitis (5 papers, 2022 to 2025). Inflammation of breast tissue during lactation or postpartum due to an obstructed duct or infection. "In summary, CB significantly mitigates inflammatory damage in LPS-induced mastitis models by suppressing inflammatory cytokine production, inhibiting apoptosis, and downregulating ARPC3, ARPC4, and HSP70 expression." (PMID 40243637, 2025). "In our previous research, proteomic analysis unveiled that LTA induces mastitis by modulating ARPC3 and ARPC4, thereby activating the host immune response." (PMID 39199289, 2024). "Our results demonstrate that CB significantly alleviates mastitis symptoms by suppressing inflammatory responses, inhibiting apoptosis, and downregulating key molecules including ARPC3, ARPC4, and HSP70, thereby providing a theoretical basis for its potential therapeutic application." (PMID 40243637, 2025). "Future studies should explore these multidimensional interactions to further elucidate the molecular mechanisms by which ARPC3/ARPC4 and HSP70 regulate bovine mastitis progression." (PMID 40305275, 2025). "Previous studies by our team have identified a potential interaction mechanism between ARPC3/4 and HSP70 in an LTA-induced bovine mastitis inflammation model." (PMID 40243637, 2025). "This research will establish a solid foundation for future studies, elucidating the regulatory roles of key factors ARPC3, ARPC4, and HSP70 in dairy cow mastitis, thereby facilitating the identification of new therapeutic targets for this condition." (PMID 39199289, 2024).
gastric cancer (3 papers, 2019 to 2024). A primary or metastatic malignant neoplasm involving the stomach. "Moreover, CK636, the small molecule inhibitor of Arp2/3 complex which has been confirmed to participate in the process by which HOXA11 regulates the migration and invasion of gastric cancer cells, could also downregulate the expression of Arpc2 and Arpc3 which were upregulated by HOXA11." (PMID 31695791, 2019). "Furthermore, we examined the mRNA expression levels of two gastric cancer biomarkers, chloride channel-3 (CLC-3) and actin-related protein 2/3 complex subunit 3 (ARPC3) (21, –, 23)." (PMID 38916312, 2024). "Taken together, these findings suggested that Twist1 and Arpc3 mRNAs are positively regulated by MYOF and that MYOF might promote the motility of gastric cancer cells." (PMID 36147922, 2022).
fungal infection (1 paper, 2022). "There is consistent evidence from studies on wild and domesticated tomato (Solanum habrochaites and S. lycopersicum) and on wheat (Triticum aestivum) that the expression of ARPC3 is induced following fungal infection." (PMID 36307477, 2022).
osteosarcoma (1 paper, 2025). A usually aggressive malignant bone-forming mesenchymal neoplasm, predominantly affecting adolescents and young adults. "Other genes, including WNT5A (AUC = 0.935), GCA (AUC = 0.922), ANXA6 (AUC = 0.909), ARPC3 (AUC = 0.909), and IL1β (AUC = 0.766) also exhibited heterogeneous levels of predictive precision for detecting osteosarcoma." (PMID 40616392, 2025). "The expression profiles of six core genes (WNT5A, GCA, ANXA6, BIRC5, IL1β, and ARPC3) were contrasted between the control and osteosarcoma groups." (PMID 40616392, 2025). "Bioinformatics analysis identified six exosome‐associated osteosarcoma genes (WNT5A, GCA, ANXA6, BIRC5, IL1β, and ARPC3) that could serve as potential biomarkers." (PMID 40616392, 2025).
Pancreatic cysts (1 paper, 2025). A cyst of the pancreas that possess a lining of mucous epithelium. "The corresponding ARPC3 protein of showed extensive interactions with other Arp2/3 complex proteins, suggesting its critical role in the malignant transformation of pancreatic cysts." (PMID 39890846, 2025).
Parkinson disease (1 paper, 2025). A progressive degenerative disorder of the central nervous system characterized by loss of dopamine producing neurons in the substantia nigra and the presence of Lewy bodies in the substantia nigra and locus coeruleus. "In contrast, the Amyg showed upregulation of genes linked to oxidative phosphorylation (Atp6v1e1, Atp5mc2, Atp6v0e2), Parkinson disease (Snca, Calm1, Slc39a10), and regulation of actin cytoskeleton (Arpc3, Nckap1, Cfl1), indicating increased mitochondrial metabolism and structural plasticity." (PMID 41394722, 2025).
psoriasis (1 paper, 2025). An autoimmune condition characterized by red, well-delineated plaques with silvery scales that are usually on the extensor surfaces and scalp. "The knockdown of ARPC3 leads to tight junction dysfunction in cells, while the knockdown of ARPC4 causes skin complications similar to psoriasis." (PMID 40305275, 2025).
Yersinia infection (1 paper, 2022). "Conclusively, the mechanisms of action of ARPC3 and ARPC4 in the invasion of cells by gram-negative bacteria have been widely reported, for example, both are involved in the pathogenic E. coli, Salmonella, and Yersinia infection pathways." (PMID 36090174, 2022).
tumor (5 papers, 2022 to 2026). "Other genes, such as ARPC3, POLR2H, WSB2, and ARL6IP5, show opposite association with response in tumor and stroma compartments, respectively." (PMID 41550766, 2026). "Cluster2 was enriched with cytoskeleton and metabolism-related factors, such as ARPC3 and CA2, where CA2 participates in regulating the cellular pH and ion balance, and its expression changes suggest significant alterations in the tumour microenvironment." (PMID 40539065, 2025). "We confirmed that reducing ARPC3 expression did not alter tumor cell proliferation, based on Ki67 expression." (PMID 35804890, 2022). "FKBP11, PHF19, ARPC3, and MS4A14 were overexpressed in tumor tissues." (PMID 35651604, 2022).
cancer (3 papers, 2021 to 2024). A tumor composed of atypical neoplastic, often pleomorphic cells that invade other tissues. "Subunits of the actin-related protein 2/3 complex (a major component of filamentous actin), ARP3 and ARPC3, may have a role in the migration of cancer cells and the development of tumors." (PMID 38248344, 2024). "To determine whether ARP2/3 mediates Ang1-driven cancer motility, we knocked down ARPC3, a subunit of ARP2/3, using ARPC3-specific shRNA in SW620 and COLO320DM cancer cells, followed by scratch assay." (PMID 35626145, 2022).
neurodegenerative disease (1 paper, 2022). A disorder of the central nervous system characterized by gradual and progressive loss of neural tissue and neurologic function. "Several regulated genes, such as Arpc3, Glp2r, Sirt3 and Per1 have been reported to exert protective effects in neurodegenerative diseases or reverse memory deficits in various models, underlining the observed protective effects of spermidine." (PMID 35780157, 2022).
psychiatric disorder (1 paper, 2023). A disorder characterized by behavioral and/or psychological abnormalities, often accompanied by physical symptoms. "Specifically, Arpc3 has been associated with developmental and psychiatric disorders and discovered to be an interactor of SCHZ genes." (PMID 37834084, 2023).
ARPC3 also shares sentences with these, for which no sentence is quoted: infection (2 papers); Ataxia (1); breast carcinoma (1); hepatocellular carcinoma (1); Intellectual disability (1); meningioma (1); pancreatic cancer (1); Salmonella Infections (1); schizophrenia (1); systemic sclerosis (1).